APOE (apolipoprotein E)
Diseases named in the same sentence as APOE in open-access papers (continued):
Sharing a sentence is not in itself a finding about the gene and the disease.
Alzheimer disease (continued). "Apolipoprotein E4 (APOE4) is a risk factor for developing Alzheimer’s disease (AD)." (PMID 39833961, 2025). "APOE variation, especially APOE ε4 allele count, is a known risk factor for Alzheimer’s disease." (PMID 39974048, 2025). "AI ancestry may protect against the deleterious effects of APOE ε4: recent work has demonstrated an attenuated effect of APOE ε4 on the risk of cognitive decline, dementia, and radiographic features of Alzheimer's disease in AI populations." (PMID 41282305, 2025). "We examined how sleep architecture relates to astrocytic, neuroaxonal and Alzheimer’s disease-related fluid biomarkers in cognitively unimpaired adults and whether age, sex and APOE ε4 moderate these associations." (PMID 41268178, 2025). "Furthermore, it was established that the association between Alzheimer’s disease risk and APOE ε4 allele dosage is less significant in Hispanic and African American populations, yet more pronounced in Japanese individuals relative to Caucasians." (PMID 40869138, 2025). "Genetic risks may be moderated by the etiology of ID and the aggregate impacts of Alzheimer’s Disease (AD) risk genes, such as apolipoprotein (APOE), on dementia outcomes." (PMID 40697576, 2025). "It has been speculated that the structural differences between the APOE genotypes could explain, at least partially, why APOE4 carriers are more susceptible to heavy metal intoxication and certain diseases, such as Alzheimer’s disease." (PMID 40085364, 2025). "The ApoE ε2 and ε3 alleles are generally considered to have a protective effect on hearing, while the ε4 allele is significantly associated with an increased risk of Alzheimer's disease." (PMID 40638992, 2025). "Specifically, ApoE genotype may modulate progression rate in Alzheimer’s disease via compensatory mechanisms unrelated to the risk of disease or the accumulation of Aß and tau or inflammation." (PMID 41278832, 2025). "Additionally, ApoE allele 4, APOE 4, is a recognized important risk factor for Alzheimer’s disease development." (PMID 40295730, 2025). "Alzheimer’s disease prevalence in Aboriginal and Torres Strait Islander people is also three to five times higher than the general Australian population, with a possible elevation in APOE ε4 allele frequency." (PMID 40588578, 2025). "Additionally, ApoE serves as a major brain cholesterol carrier and is the strongest risk locus for late-onset Alzheimer's disease, facilitating the deposition and accumulation of amyloid plaques." (PMID 40495209, 2025). "Different alleles of the apolipoprotein E (ApoE), a protein involved in lipid transport, fat metabolism, and brain injury repair, are recognized as important polygenic risk factors for both Alzheimer’s disease (AD) and CAA." (PMID 41035821, 2025). "The ε4 allele of the apolipoprotein E (APOE) gene strongly increases Alzheimer’s disease (AD) risk, though its molecular mechanisms remain unclear." (PMID 41516176, 2025). "APOE: The APOE gene is closely linked to human longevity and plays a crucial role in lipid metabolism, with significant variations affecting the lifespan and Alzheimer’s disease (AD) risk." (PMID 40006994, 2025). "The overlapping effects of APOE on both PD and Alzheimer's Disease (AD), despite their distinct causes, may arise from shared neurodegenerative pathways." (PMID 41180817, 2025). "•APOE ε4 modified the impact of the EAT-Lancet diet on Alzheimer's disease (AD) risk." (PMID 40222839, 2025). "Alzheimer’s disease (AD) risk variants have been identified in European ancestry cohorts that have stronger effects at certain ages, in individuals with a specific sex, or in those with specific isoforms of APOE, the strongest AD risk locus." (PMID 40708016, 2025). "The study aims to assess the association of apolipoprotein E (APOE) gene polymorphisms with serological lipid and inflammatory markers to determine their potential role in predicting the risk of cardiovascular diseases (CVDs) and Alzheimer's disease (AD)." (PMID 38903305, 2024).
Alzheimer disease (continued). "The APOE e4 allele is a well-known risk factor for Alzheimer’s disease (AD) and CAA stages." (PMID 39195563, 2024). "The authors then tested whether two genetic factors—APOE ɛ4, and a global PRS for Alzheimer’s disease (excluding the APOE region)—influenced participants’ risk of transitioning between these biomarker stages." (PMID 39018494, 2024). "Elevated levels of APOE increase an individuals’ risk of developing Alzheimer's disease." (PMID 39498386, 2024). "Emerging evidence suggests that APOE polymorphisms may be implicated in the development and progression of various neurodegenerative diseases, including Alzheimer’s disease (AD), Parkinson’s disease, and multiple sclerosis." (PMID 38275738, 2024). "ApoE, one of the major proteins associated with Alzheimer’s Disease and represents one example of where crosstalk with a neurodegenerative disease might provide a novel approach to TBI therapeutics." (PMID 39450122, 2024). "The apolipoprotein E (APOE) ε4 genotype increases the risk of Alzheimer’s disease (AD)." (PMID 38880878, 2024). "APOE, an apolipoprotein predominantly recognised for its involvement in cholesterol metabolism, has been linked to several disorders, such as cardiovascular disease and Alzheimer's disease." (PMID 39187937, 2024). "Also, we included genotyping of the APOE ε4 allele in a large subsample of participants to reduce potential confounding attributed to this well-known risk factor for Alzheimer disease." (PMID 38709531, 2024). "Given the role of APOE e4 in Alzheimer’s disease, this may modulate the risk of dementia via Alzheimer’s disease pathology in at least a subset of the LBD-D cases; however, previous work has been inconsistent." (PMID 38978726, 2024). "Interestingly, several of these SNPs are in genes implicated in Alzheimer's disease (AD), such as apolipoprotein E (ApoE), catechol‐O‐methyltransferase (COMT), and brain‐derived neurotrophic factor (BDNF)." (PMID 38234228, 2024). "The joint effects of APOE genotype and DNA methylation on Alzheimer disease (AD) risk is relatively unknown." (PMID 38424036, 2024). "The APOE gene is the strongest genetic risk factor for late-onset Alzheimer’s Disease (LOAD)." (PMID 39210471, 2024). "However, all CETP inhibitors, including the novel CETP-inhibitor obicetrapib, increase plasma concentrations of apolipoprotein-E (Apo-E), which is associated with decreased risk of dementia, in particular for Alzheimer’s disease (AD)." (PMID 39415269, 2024). "The ApoE 4 polymorphism is the strongest genetic risk factor for Alzheimer’s disease." (PMID 39202269, 2024). "The ε4 allele of the apolipoprotein E gene (APOE4) is recognized as a significant risk factor for developing Alzheimer’s Disease due to its association with astrocytic/microglia activation and alterations of vascular mural cells leading to endothelial disruption and decreased amyloid clearance." (PMID 39314625, 2024). "Abnormal methylation of the apolipoprotein E (APOE) gene has been found to be associated with Alzheimer’s disease, which might have overlapping mechanisms with ASD." (PMID 39199432, 2024). "APOE-4 is a significant genetic risk for Alzheimer’s disease." (PMID 38605880, 2024). "The APOE genotype is the most important genetic risk factor for Alzheimer’s disease." (PMID 39062996, 2024). "The APOE ε4 allele is among the genetic factors most closely linked with Alzheimer’s disease, and individuals carrying the APOE ε4 allele have a greater risk of developing Alzheimer’s disease." (PMID 38456011, 2024). "However, premature stop codon mutations in APOE were analyzed using data from the Alzheimer’s Disease Sequencing Project (ADSP), revealing truncation variants, including Trp5Ter, Leu8Ter, and Gln39Ter, in cognitively healthy individuals aged 71 to 90 years." (PMID 39596030, 2024). "APOE-ε4 is well known for its associations with Alzheimer’s Disease and cardiovascular disease." (PMID 39132489, 2024).
Alzheimer disease (continued). "APOE alleles confer different risks for Alzheimer’s disease." (PMID 39149469, 2024). "We were particularly interested in the genetic risk factor for Alzheimer’s Disease, APOE-ε4." (PMID 37163077, 2024). "Transgenic mice with high levels of the apolipoprotein E gene APOE4 (a risk factor for Alzheimer's disease) and given a diet with low docosahexaenoic acid (an omega-3 fatty acid) had olfactory loss and memory loss along with an increase in IBA-1, an inflammatory factor, in the olfactory bulb." (PMID 39464255, 2024). "Beyond APOE, Alzheimer’s disease is associated with MTHFR and ACE polymorphisms." (PMID 38790930, 2024). "Given the risk associated with HFD/HSD for cardiovascular disease, Alzheimer’s disease, and early dementia, we hypothesized ApoE ε4 male and female rats would show exacerbated signs of cognitive dysfunction." (PMID 39506641, 2024). "Sex differences are seen in patients with Alzheimer’s disease who are carriers of ApoE ε4 allele." (PMID 38312931, 2024). "Consequently, therapies specifically designed to target the ApoE ε4 allele have shown success in preventing Alzheimer’s disease." (PMID 39596378, 2024). "A relationship between PM2.5-derived hypomethylation and Alzheimer’s disease, especially methylation changes associated with amyloid precursor protein, beta-site amyloid precursor protein cleaving enzyme 1, and the apolipoprotein E gene, has also been reported." (PMID 39251997, 2024). "APOE gene polym orphisms have been linked to Alzheimer’s disease and coronary heart diseases." (PMID 39763652, 2024). "Notably, in contrast to Alzheimer’s disease (AD), we observed the APOE ε2 allele to be the risk allele in PSP." (PMID 39152475, 2024). "Finally, TOMM40L is in linkage disequilibrium with APOE and contributes synergistically to the risk of Alzheimer’s Disease." (PMID 39760516, 2024). "The ε4 allele of the APOE gene heightens the risk of late onset Alzheimer’s disease." (PMID 38802684, 2024). "The ApoE-Є4 allele (frequency of 0.16 in SiGN) has been associated with numerous adverse health outcomes, including hyperlipidemia and lipid metabolism, Alzheimer’s disease and dementia, and coronary disease." (PMID 39286457, 2024). "The different outcomes depend, for example, on the duration of treatment, on estrogen replacement therapy (ERT) only or combined HRT (estrogen and progestogen) and also if the study involved women possessing the APOE-ε4 allele, which contains susceptible genes for Alzheimer’s disease." (PMID 39046467, 2024). "Using postmortem inferior temporal brain cortex tissue from deceased subjects from the Rush Memory and Aging Project (MAP) (N = 608), we found that the association of iron with pathologically confirmed clinical Alzheimer’s disease was stronger among those with the adverse APOE-ε4 allele." (PMID 35484240, 2024). "The APOE-ε4 allele(s) is a strong risk factor for Alzheimer’s disease (AD)." (PMID 38225507, 2024). "Apolipoprotein E ɛ4 (APOE4) is the strongest genetic risk factor for Alzheimer’s disease (AD)." (PMID 38634644, 2024). "APOE ɛ4 allele is the major genetic risk factor for Alzheimer’s Disease (AD)." (PMID 39012674, 2024). "Influence of the APOE region on trait-Alzheimer’s disease (AD) associations." (PMID 38787369, 2024). "The major genetic risk factor for Alzheimer’s disease (AD), APOE4, accelerates beta-amyloid (Aβ) plaque formation, but whether this is caused by APOE expressed in microglia or astrocytes is debated." (PMID 39528861, 2024). "The APOE gene has long been associated with Alzheimer Disease (AD) risk." (PMID 39149451, 2024). "Apolipoprotein E (APOE) ε4 is associated with poorer early symptoms of Alzheimer's disease (AD)." (PMID 37697966, 2024). "Apolipoprotein E4 (APOE4) carriers’ tendency toward hypercholesterolemia may contribute to Alzheimer's disease (AD) risk through oxysterols, which traverse the blood‐brain barrier." (PMID 38574442, 2024).
Alzheimer disease (continued). "The pathogenic role of APOE gene ε4 in Alzheimer’s disease (AD) is still debated, with some studies suggesting a toxic gain of function in its interaction with Aβ, while other effects may result from the loss of protective function." (PMID 38790930, 2024). "We aimed to develop and validate a protein risk score for predicting Alzheimer's disease (AD) and compare its performance with a validated clinical risk model (Cognitive Health and Dementia Risk Index for AD [CogDrisk‐AD]) and apolipoprotein E (APOE) genotypes." (PMID 39252463, 2024). "As expected, APOE Ɛ4 dosage was significantly and positively associated with the risk of incident vascular dementia (2 vs. 0; adjusted HR: 5.81; 95%CI: 4.72, 7.15), and incident Alzheimer’s disease (2 vs. 0; adjusted HR: 12.05; 95%CI: 10.54, 13.77)." (PMID 37689747, 2023). "The sex stratified association between Alzheimer’s disease and APOE ε4 allele and genotypes." (PMID 37680541, 2023). "APOE (ε4 isoform) is a primary risk factor for the onset of Alzheimer’s disease (AD)." (PMID 37830571, 2023). "Specifically, the E4 allele of the APOE gene is a recognized risk factor for Alzheimer’s disease." (PMID 38003309, 2023). "Surprisingly, when estimating overall risk for cognitive impairment, lifetime incarceration was associated with a risk level that fell between the risk associated with carrying one and two copies of the APOE-ε4 allele—the strongest genetic risk factor for Alzheimer’s disease." (PMID 38048316, 2023). "Moreover, for more than 10 years, it has been known from studies in mouse models and humans that Alzheimer’s disease-related pathology and epilepsy share the association with specific ApoE genotype." (PMID 37965047, 2023). "For example, APOE4 genotype confers transcriptomic and functional alterations in primary mouse microglia in vitro, while microglia-specific ApoE loss reduces A-beta plaque size in a mouse model of Alzheimer’s disease." (PMID 36890585, 2023). "Consistent with this hypothesis, common genetic variation at the apolipoprotein E (APOE) locus that increases risk for Alzheimer’s disease has also been consistently and robustly associated with PD age at onset and the development of PD dementia." (PMID 36100231, 2023). "In addition, it is shown that the APOC1 insertion allele, in combination with APOE ε4, likely served as a potential risk factor for developing Alzheimer’s disease." (PMID 36970281, 2023). "From a biological perspective, individuals that have the ε4 allele of the apolipoprotein E gene (APOE4) are at substantially increased risks of developing Alzheimer’s disease, Lewy body disease, cerebrovascular disease, and accelerated age-related cognitive decline." (PMID 37371340, 2023). "A growing body of evidence suggests that TOMM40, a gene located next to APOE on chromosome 19, may influence the risk of developing Alzheimer’s disease (AD)." (PMID 37718796, 2023). "While the APOE4 allele is thought to cause mitochondrial dysfunction in Alzheimer’s disease, our study places mitochondria upstream of APOE, uncovering a novel function for these multifaceted organelles." (PMID 37171075, 2023). "That the APOE-ε4 allele predisposes to all of Alzheimer’s dementia, DP, CTE, and TBI confirms that there is a common element in the pathogenesis of these conditions, and that this element may be vascular; we suggest vascular fragility." (PMID 36950132, 2023). "The age stratified association between Alzheimer’s disease and APOE ε4 allele and genotypes." (PMID 37680541, 2023). "LRP1B also plays a role in removing β-amyloid across the blood–brain barrier, and its reduced or absent expression may result in decreased clearance of β-amyloid and ApoE/α2-macroglobulin complexes, thereby increasing the risk of Alzheimer’s disease." (PMID 37630190, 2023).
Alzheimer disease (continued). "Apolipoprotein E (ApoE), a class of lipoproteins responsible for cholesterol transport and lipoprotein metabolism, is the strongest genetic risk factor for the late-onset Alzheimer Disease (LOAD) and emerging therapeutic targets for it." (PMID 38075287, 2023). "Women in the lowest tertile of fasting insulin showed a higher prevalence of the APOE-4 allele compared to women with higher insulin, which is remarkable as the APOE-4 allele is the strongest genetic risk factor for dementia, particularly Alzheimer’s disease." (PMID 37420130, 2023). "The APOE ε4 allele has been identified as a major genetic risk factor for Alzheimer’s dementia (AD) and could exacerbate obesity’s impact on cognitive function." (PMID 35921193, 2023). "The APOE ε4 allele is the primary genetic risk factor for late-onset Alzheimer’s disease." (PMID 37759733, 2023). "FABP7 is also proposed to functionally interact with sortilin, the neuronal receptor for apolipoprotein E (apoE), with apoE3 leading to expression of FABP7 but the apoE4 variant, a major risk factor for Alzheimer’s disease, being associated with reduced FABP7 levels." (PMID 37207357, 2023). "Notably, microglial and innate immune mechanisms have also been strongly implicated in Alzheimer’s disease, including downstream of APOE, an important PD modifying gene." (PMID 36100231, 2023). "Overall, these data suggest being overweight by BMI standards may preserve hippocampal function, but obesity reduces hippocampal structure and function in older African Americans with the APOE- ε4 Alzheimer’s disease risk allele." (PMID 37731955, 2023). "ApoE is also strongly involved in Alzheimer’s disease (AD) with its alleles (ε2, ε3, and ε4)." (PMID 38137454, 2023). "Apolipoprotein-E (APOE) ε4 is a major genetic risk factor for Alzheimer’s disease (AD)." (PMID 37065463, 2023). "Using data from the Health and Retirement Study, we found that incarceration and APOE-ε4 genotype (i.e., the chief genetic risk factor for Alzheimer’s disease) both constituted substantive risk factors for cognitive impairment in terms of overall risk and earlier onset." (PMID 38048316, 2023). "Besides known causative gene mutation, the ε4 allele of the apolipoprotein E gene (APOE) is the strongest genetic risk factor for sporadic Alzheimer’s disease." (PMID 36850008, 2023). "In an analysis taking the competing risk of Alzheimer’s disease into account, type 2 diabetes was significantly associated with all-cause dementia in APOE ε4 carriers, which shows that our hypothesis might be true." (PMID 37091584, 2023). "Interestingly, the strongest genetic risk factor for Alzheimer’s disease, APOE, was also modulated in pericytes and neurons." (PMID 36873109, 2023). "Patients with traumatic brain injury (TBI) are at an increased risk of developing chronic neurodegenerative diseases, including Alzheimer's disease (AD), an association thought to be related to several factors, including altered production and clearance of apolipoprotein E (ApoE) and amyloid-β (Aβ)." (PMID 37355618, 2023). "Additionally, genetic variation such as apolipoprotein E, which was associated with the risk of Alzheimer’s disease, has shown a variable interaction with mild traumatic brain injury." (PMID 37743466, 2023). "Vascular factors are known to be early and important players in Alzheimer’s disease (AD) development, however the role of the ε4 allele of the Apolipoprotein (APOE) gene (a risk factor for developing AD) remains unclear." (PMID 37350319, 2023). "The apolipoprotein E (APOE) gene is a known Alzheimer’s disease (AD) risk factor that may alter the course of WM degeneration." (PMID 36908785, 2023).